DKK3 (dickkopf Wnt signaling pathway inhibitor 3)
Diseases named in the same sentence as DKK3 in open-access papers (continued):
Sharing a sentence is not in itself a finding about the gene and the disease.
tumor (continued). "DKK3, a type 1 tumor cell marker, was localized in the center and surrounding area of the wheel structure." (PMID 39483146, 2024). "Recent studies highlighted a protective and tumor suppressor role of stromal Dickkopf-3 (DKK3), a secreted glycoprotein that belongs to the DKK family of proteins in PCa." (PMID 36845147, 2023). "Previous studies propose that DKK3 has a tumor-suppressor role, through its ability to induce dendritic cell differentiation and activation of T cells." (PMID 38022675, 2023). "Our previous findings indicate that REIC/Dkk-3 acts as a very strong tumor suppressor in multiple types of cancer." (PMID 36869893, 2023). "In sum, these in vivo data reveal that DKK3 can restrict adaptive antitumor immunity during multiple stages of tumor progression." (PMID 37847565, 2023). "According to a study conducted in 2018, high expression of miR-183/182/96 in RCC facilitates the proliferation and invasion of tumor cells by targeting Dickkopf-related protein-3 (DKK-3), which is a negative regulator of the Wnt signaling pathway." (PMID 37834162, 2023). "We observed differences in DKK3 expression among the 12 GBM samples; as the tumor grade increased, the overall expression of DKK3 decreased." (PMID 37149563, 2023). "Overexpression of Dickkopf‐3 (DKK‐3), another Wnt signaling antagonist, retards tumor growth and lung metastasis in xenograft models." (PMID 37441462, 2023). "We have observed that the tumor-suppressing effect of REIC/Dkk-3 protein in mouse models is far higher in MDA-MB-231 cells than that in Colon-26 cells (our unpublished data)." (PMID 36869893, 2023). "In conclusion, our present study proposes a novel function of the REIC/Dkk-3 protein: a negative regulation of PD-L1 on the cancer cell surface as a tumor-suppressive effect that acts against PD-L1-mediated cancer immune evasion." (PMID 36869893, 2023). "Silencing DKK3 expression promotes cell motility and inhibits tumor clonal development, but has little effect on cell viability." (PMID 38269250, 2023). "This is achieved via early initiation of a CD4+/Treg–skewed T cell response, and we provide evidence that the tumor-derived Wnt modulator DKK3 is critical to this process." (PMID 37847565, 2023). "Immunohistochemical staining confirmed extreme polarization of podoplanin, DKK3 and C3 expression in relation to tumor proximity." (PMID 37350578, 2023). "Zebularine can be incorporated into DNA and form covalent complexes with DNMT to competitively inhibit DNMT activity, demethylate tumor suppressor genes, such as SFRP2, Dkk3, and p16, and inhibit tumor cell proliferation, differentiation, and metastasis." (PMID 37056286, 2023). "Intriguingly, DKK-3 appears to have immunomodulatory functions and a complex role in cancer, acting as either a tumor suppressor or an oncogene, depending on the context." (PMID 38201279, 2023). "The Wnt signaling inhibitor DKK3 is known as a potential key player in tumor suppression, and the expression of DKK3 is found to be frequently downregulated in almost any cancer entity." (PMID 37149563, 2023). "The intravenous administration of REIC/Dkk-3 recombinant protein significantly worked to stall the engrafted tumor outgrowth in a dose-dependent manner." (PMID 36869893, 2023). "We discovered that DKK3 acts as a tumor suppressor gene in LGG by increasing tumor microenvironmental immunity whereas, as an oncogene in GBM by inducing an immunosuppressive microenvironment." (PMID 37149563, 2023). "Fewer anti-eGFP antibodies were also present in the serum of mice bearing DKK3-expressing D2A1 tumors when accounting for tumor volume." (PMID 37847565, 2023). "Podoplanin was expressed on stroma that encased tumor whilst DKK3 expression was present both within tumor and tumor-proximal stroma." (PMID 37350578, 2023).
tumor (continued). "Shown as within patient mean normalized count vs region type for DEG identified in A. (D) Representative immunohistochemical staining of podoplanin, DKK3 and C3 proteins in relation to tumor cells (T) in PDAC tissue." (PMID 37350578, 2023). "Coculture of TNF-α-pre-stimulated human bone marrow MSCs with MDA tumor cells induced tumor cell apoptosis via the secretion of DKK3, which inhibited the cyclins D1 and D3, and increased P21 expression in the tumor cells." (PMID 36814921, 2023). "DKK-3 is also expressed in pancreatic stellate cells, where it promotes resistance to chemotherapy, tumor growth and metastatic spread, via both paracrine and autocrine mechanisms, through NF-κB activation." (PMID 38201279, 2023). "When analyzed using TCGA data, we found that contrary to our expectations, DKK3 expression levels decreased with increasing tumor grade." (PMID 37149563, 2023). "The inhibitory effect of DKK-3 on the Wnt pathway implies a potential tumor suppressor role due to the prevalent pro-oncogenic impact of Wnt pathway overactivation." (PMID 38201279, 2023). "With this model, we observed marked tumor suppression with a significant downregulation of PD-L1 in cancer cells in the tumors in the REIC/Dkk-3 treated mice." (PMID 36869893, 2023). "We also demonstrate that DKK3 is essential for tumor survival during the latent phase and generally protects tumors from antigen-specific CD8+ T cell immunity." (PMID 37847565, 2023). "We found direct evidence that tumor-derived DKK3 was able to induce Treg differentiation in vitro, which ultimately resulted in decreased CD8+ T cell function." (PMID 37847565, 2023). "Rather, our results suggest that DKK3 acts as a tumor suppressor gene in LGG by increasing tumor microenvironmental immunity, but as an oncogene in GBM by decreasing it." (PMID 37149563, 2023). "Most importantly, our data further confirmed that ApoG2 suppressed CC cell proliferation, invasion and EMT process, as well as tumor growth by upregulating DKK3." (PMID 35924156, 2022). "One aim of this review is to highlight the potential role of Dkk-3, and in particular, stromal Dkk-3, as a component of the tumor microenvironment." (PMID 36497305, 2022). "In one study, overexpression of CCL28 (inflammatory chemokine) and underexpression of DKK3 (a tumour suppressor and prognostic marker) were predictive of pCR." (PMID 35205743, 2022). "Dickkopf-3 (DKK3) is considered a tumor suppressor as it possesses anti-tumoral properties and is frequently downregulated in various cancers." (PMID 35205672, 2022). "This review focuses on the roles of Dkk-3 in the tumor microenvironment and the effects of modulating Dkk-3 in different settings." (PMID 36497305, 2022). "Herein, we observed an inverse relationship of the content of miR‐363‐3p with DKK3 in PCa tumor tissues and exhibited DKK3 as a downstream direct target of miR‐363‐3p." (PMID 35303365, 2022). "In pathway-based network analysis, DKK3 was directly linked to the THY1 gene, a tumor suppressor gene." (PMID 35599254, 2022). "In this study, the peptides successfully induced a significant reduction in DKK3-driven Akt phosphorylation, cellular proliferation, migration, and in vivo tumor growth." (PMID 36376957, 2022). "It is also reported that DKK3 inhibits other Wnt transduction pathways such as the Wnt/JNK signaling pathway in tumor cells." (PMID 35303365, 2022). "In conclusion, we have established a DKK3 specific inhibitory peptide that can suppress tumor proliferation, migration, and invasion at low doses." (PMID 36376957, 2022). "Untergasser reported that Dkk-3 is expressed in tumor endothelial cells and supports capillary formation." (PMID 36006934, 2022). "Next, we analyzed the protein expression of DKK3 in CC in collected 51 paired tumor and adjacent tissues by performing immunohistochemical staining." (PMID 35924156, 2022).
tumor (continued). "The inhibitory peptides for CRD1 and CRD2 of DKK3 significantly reduced the phosphorylation of Akt, and consequently suppressed cellular proliferation, migration, invasion and in vivo tumor growth at very low doses." (PMID 36376957, 2022). "In human OSA cell lines, and in xenograft mice, DKK3 expression was reduced, however subsequent restoration of DKK3 expression resulted in reduced tumor and metastatic growth." (PMID 36570509, 2022). "DKK3 is a tumor suppressor gene, known to be involved in the Wnt pathway, with an inhibitory effect on the canonical TGFβ signaling." (PMID 35739280, 2022). "Next, the anti-proliferative effect of DKK3 was evaluated in three-dimensional (3D) tumor spheroids of OV-90 and OV-90/PTX formed in the microwell arrays." (PMID 35205672, 2022). "Since then, DKK3 has been described to be a tumor suppressor gene, although this is clearly not generally the case in some contexts." (PMID 36497305, 2022). "Statistical analysis further indicated increased weaker staining of DKK3 protein in paraffin-embedded tumor tissues, in comparison with that in adjacent tissues." (PMID 35924156, 2022). "Reduced expression in immortalized cells/Dickkopf-3 (REIC/Dkk-3) is a tumor suppressor and its overexpression has been shown to exert anti-tumor effects as a therapeutic target gene in many human cancers." (PMID 36006934, 2022). "By contrast, we observed significantly decreased moderate and strong staining of DKK3 protein in tumor tissues compared with adjacent tissues." (PMID 35924156, 2022). "It is reported that DKK3 functions as a negative regulator of oncogenic Wnt signaling and, is therefore, considered to be a tumor suppressor gene." (PMID 36376957, 2022). "Anti-CKAP4 antibodies that inhibit the binding of Dkk-3 to CKAP4 reduce tumor formation induced by ESCC cells in xenograft assays." (PMID 36497305, 2022). "This review compares the various functions of Dkk-3 in the tumor microenvironment, where Dkk-3 has been found to be expressed by subpopulations of fibroblasts, endothelial, and immune cells, in addition to epithelial cells." (PMID 36497305, 2022). "Reversal of DKK3 gene promoter methylation by demethylating reagents such as decitabine and zebularine or using a CRISPR-based approach results in increased Dkk-3 protein levels and can reduce tumor cell proliferation and migration." (PMID 36497305, 2022). "DKK3 is a member of the Dickkopf family, which is decreased in a variety of cancers serving as a tumor suppressor gene." (PMID 34631806, 2021). "Activation of P-TEFb upon DKK3 overexpression further strengthens its role as potential tumor suppressor." (PMID 33670899, 2021). "We have previously reported high expression of MDR1 in GBM and demonstrated that down-regulation of MDR1 via Akt/NF-κB pathways upon transfection of the Ad-DKK3 gene augmented the anti-tumor effects of temozolomide in GBM cells and in a GBM-xenograft model." (PMID 34301977, 2021). "Nevertheless, the result of these alterations is important in studying the tumor suppression function of DKK3." (PMID 33670899, 2021). "The method takes advantage of the adenovirus as a vector for the tumor suppressor gene DKK-3 and induces its expression to increase apoptosis and further tumor growth reduction." (PMID 34451907, 2021). "Expression of the DKK1 and DKK3 gene is controlled, among other mechanisms, by DNA methylation, a common epigenetic silencing tool, which is increased in many tumors and tumor cell lines." (PMID 34064046, 2021). "In support of our previous studies and other researchers’ findings, DKK3 was confirmed to inhibit BxPC-3 cell proliferation and induce tumor cell apoptosis." (PMID 34391478, 2021). "Of note, the most prominently reported function of DKK-3 in cancer is as a tumor suppressor since it is known to have reduced expression in immortalized cells." (PMID 34451907, 2021).
tumor (continued). "Several of the top downregulated genes are bona fide or presumed tumor suppressor genes, including Dkk1 and Dkk3 (Wnt signaling antagonists)." (PMID 34638267, 2021). "Given that Dkk3 is a tumor suppressor and its expression is significantly lower in a variety of human cancer types." (PMID 34124998, 2021). "The authors attributed this inconsistency to the expression of DKK-3 in tumor neo-vasculature, which highlighted the difficulties in defining the ideal sample to be analyzed." (PMID 34451907, 2021). "DKK3 overexpression reduced tumor angiogenesis in ovarian cancer by interfering with VEGFR-2/Akt/mTOR phosphorylation mediated by B2 microglobulin." (PMID 33670899, 2021). "Although β-catenin-mediated Wnt signaling is dispensable for the function of CAFs in remodeling the ECM and promoting tumor cell proliferation and invasion, DKK3-driven YAP activation is necessary to induce a tumor-promoting phenotype." (PMID 32546182, 2020). "In the current study, we analysed the discrepant expression between miR-425 and DKK3 in BC tumour tissues, then predicted and identified that DKK3 was a direct downstream target of miR-425." (PMID 32284738, 2020). "As a divergent member of the Dickkopf (DKK) family, the Dickkopf-related protein 3 (DKK3) is a tumor suppressor involved in slowing down the progressions of many types of cancer." (PMID 33013201, 2020). "MYCN also regulates the expression of a tumor suppressor, Dickkopf‐3 (DKK3), a secreted glycoprotein in culture supernatants, by transcriptionally activating the expression of mir‐92 in NB cells." (PMID 31637848, 2020). "A reciprocal mechanism has been described for the Wnt-inhibitor Dickkopf-3 (DKK3) which induces tumor cell maturation and correlates with a favorable prognosis." (PMID 33585251, 2020). "Within OSA there are conflicting reports; in OSA cell lines and xenograft mice, DKK3 expression was shown to be downregulated, with subsequent restoration of DKK3 expression reducing tumor and metastatic growth." (PMID 32854182, 2020). "This is consistent with other studies such as in a tumor microenvironment where DKK3 and Kremen-1 colocalized to internal structures; however, after DKK3 silencing, Kremen-1 localized to the cell periphery." (PMID 32331523, 2020). "The results from the current study showed that DKK3 was more highly expressed in OSA tissue than in non-tumor tissue." (PMID 32854182, 2020). "To characterize the tumor suppressor function of DKK3, we chose 3 cell lines, which showed reduced DKK3 expression and were invasive in nature." (PMID 31737564, 2019). "We used GBC cell lines to perform functional assays to demonstrate the tumor suppressor property of DKK3." (PMID 31737564, 2019). "To validate potential tumor suppressor property of DKK3, we further assessed expression of DKK3 on mRNA and protein level in 6 GBC cell lines using RT-PCR and western blot, respectively." (PMID 31737564, 2019). "Conversely, ectopic expression of DKK3 in NF significantly increased their ability to promote tumour growth in vivo." (PMID 30631061, 2019). "As DKK3 was restricted to CAFs in tumours, we investigated the prognostic potential of whole tumour DKK3 expression." (PMID 30631061, 2019). "miR-183 promotes tumor cell proliferation and invasion by targeting Dickkopf-related protein-3 (DKK-3), a negative regulator of the Wnt signaling pathway, and the tumor suppressor protein phosphatase 2A, one of the main regulators of AKT signaling." (PMID 31013896, 2019). "In the present study, we investigated the role of DKK3 as a tumor suppressor in GBC using in vitro model." (PMID 31737564, 2019). "Our results suggest that expression of DKK3 is significantly reduced in tumor samples compared to adjacent normal patient samples." (PMID 31737564, 2019). "DKK3 gene and protein expression is significantly upregulated in the tumour stroma in several types of cancers including breast, colon and ovarian." (PMID 30631061, 2019).
tumor (continued). "Whereas β-catenin is dispensable for CAF-mediated ECM remodelling, cancer cell growth and invasion, DKK3-driven YAP/TAZ activation is required to induce tumour-promoting phenotypes." (PMID 30631061, 2019). "This indicated that it would be meaningful to explore the functional roles of miR-92a and DKK3 in OS tumor progression." (PMID 30926679, 2019). "Consistent with this, examination of Dkk-3 expression in prostate stroma in benign and tumor sections revealed a significant reduction in the levels of Dkk-3 in tumor stroma, compared to that in stroma of benign tissue." (PMID 29858602, 2018). "Statistical analysis indicated that Dkk-3 expression was not only lower in tumor epithelium than in benign epithelium, but was also lower in tumor stroma than in benign stroma." (PMID 29858602, 2018). "In contrast to the increased DKK3 protein levels in murine tumour tissues, both p‐GSK3β and nuclear β‐catenin expression decreased after MYCN shRNA treatment." (PMID 29673070, 2018). "It remains to be determined if PTGS2 upregulation plays a role in the tumor-suppressive effects of DKK3." (PMID 29843383, 2018). "An example of a patient with moderate Dkk-3 expression in benign epithelium and low Dkk-3 expression in tumor epithelium and tumor stroma, with some expression in endothelial cells is shown in." (PMID 29858602, 2018). "DKK-3 is also expressed in various adult tissues and acts as a tumor suppressor of different malignancies." (PMID 29695980, 2018). "Consistently, inhibition of this pathway, for example through restoration of endogenous inhibitors such as WIF-1 and Dkk-3 resulted in tumor regression, increased apoptosis and reduced cell motility both in vitro and in vivo." (PMID 29534536, 2018). "The DKK3 gene product, Dickkopf-3 (Dkk-3), plays a role in prostate gland architecture and displays potent tumor suppressor activity." (PMID 29843383, 2018). "Dickkopf protein-related protein 3 (Dkk-3), is one of the most promising tumor suppressor molecules able to modulate the Wnt pathway." (PMID 28978116, 2017). "In this study, we utilized comprehensive genetic, epigenetic, and functional approaches to identify and characterize a potential tumor suppressor role for DKK3 in adrenal carcinogenesis." (PMID 28249601, 2017). "Dkk-3 was initially identified as a tumor suppressor, and was also shown to be involved in epithelial cell senescence, and acinar cell differentiation and morphogenesis." (PMID 28352232, 2017). "Unlike its ubiquitous expression in somatic cells, silencing of the Dkk3 gene is common in cancer and ectopic over-expression of DKK3 arrests tumor cell growth." (PMID 28738084, 2017). "Unfortunately, the inability of DKK3 to block Wnt receptor assembly due to steric hindrance poses a significant challenge to our understanding of its tumor suppressor function." (PMID 28738084, 2017). "Despite its inability to disrupt Wnt receptor binding, DKK3 is the best-known tumor suppressor in the family." (PMID 28738084, 2017). "To date, the most evident and consistent anti-tumor effect of Dkk-3 is its inhibitory capacity on cancer cell growth." (PMID 28978116, 2017). "More recent studies have demonstrated that Dkk-3 acts as a differentiation factor involved in remodeling of tumor vasculature." (PMID 28352232, 2017). "Studies carried out in tumor cell lines have shown that Dkk-3 enhanced phosphorylation of Smad3, a molecule that lies along the signaling pathway activated by TGF-β1." (PMID 28352232, 2017). "We demonstrated that REIC/Dkk-3 was not only an anti-cancer agent that induces tumour specific apoptosis but also restores AR signalling in both CHP-1 and human androgen-independent prostate cancer PC3 cells." (PMID 28599655, 2017). "It is the only unambiguous tumor suppressor in the family, and a diverse literature links DKK3 and tumor suppression to the ß-catenin pathway." (PMID 28738084, 2017).